WNT2 (Wnt family member 2)
Diseases named in the same sentence as WNT2 in open-access papers (continued):
Sharing a sentence is not in itself a finding about the gene and the disease.
glioma (12 papers, 2012 to 2024). A benign or malignant brain and spinal cord tumor that arises from glial cells (astrocytes, oligodendrocytes, ependymal cells). "These genes attracted our attention because Bcl-2 has been reported to be a direct target of miR-136-5p, while both Wnt2 and Bcl-2 have been linked to the pathogenesis of glioma." (PMID 29152149, 2017). "When silencing Wnt2 and β-catenin by siRNA in the human glioma U251 cells, proliferation and invasion were inhibited and apoptotic cell death was induced." (PMID 38672638, 2024). "CRNDE promotes glioma malignancy by acting as ceRNA and blocking the downregulation of Bcl-2 and Wnt2 mediated by miR-136-5ps (Li D.-X." (PMID 35359593, 2022). "Our results suggest that CRNDE functions as a ceRNA to promote glioma malignancy by indirectly inducing Bcl-2 and Wnt2 expression through binding and repression of miR-136-5p." (PMID 29152149, 2017). "Overexpression of WNT1 and WNT3a in glioma stem cells has been shown in the malignant transformation and progression of high-grade gliomas, WNT2 and WNT5 are also overexpressed in glioma." (PMID 28620312, 2017). "We therefore propose that CRNDE functions as a competing endogenous RNA (ceRNA) that binds to and negatively regulates miR-136-5p, thereby protecting Bcl-2 and Wnt2 from miR-136-5p-mediated inhibition in glioma." (PMID 29152149, 2017). "Further bioinformatics analyses using TargetScan, miRanda, and DAVID identified Bcl-2 and Wnt2 as downstream targets of miR-136-5p in gliomas." (PMID 29152149, 2017). "Silencing β-catenin, Wnt-2, and Pygo-2 expression demonstrated the involvement of Wnt/β-catenin signalling in the proliferation of U251 glioma cell line." (PMID 22400111, 2012). "In addition, the growth of tumor was delayed when nude mice which be subcutaneously inoculated with U251 glioma were treated with siRNA targeting Wnt2 and β-catenin." (PMID 35935338, 2022). "Wnt2 and β-catenin (the key mediator) were knocked down by siRNA in the human glioma U251 cells." (PMID 35935338, 2022). "The over-expression of Frizzled2, Wnt2, β-Catenin, and Wnt5a are observed in gliomas." (PMID 35935338, 2022). "Knockdown of Wnt2 and β-catenin in human U251 glioma cells could inhibit cell proliferation and induced apoptotic cell death." (PMID 31412883, 2019). "Moreover, silencing the expression of Wnt-2, Wnt-5a, and Fz-2 in the U251 glioma cell line decreases invasion." (PMID 22400111, 2012). "In addition, higher expressions of Frizzled2, Wnt2, β-Catenin and Wnt5a were observed in gliomas." (PMID 38672638, 2024). "Our in vitro experiments in glioma cells confirmed that changes in the expression of CRNDE and miR-136-5p result in changes in Wnt2 and Bcl-2 expression at the mRNA and protein levels, although our study did not provide direct evidence for the corresponding miRNA/mRNA interactions." (PMID 29152149, 2017).
melanoma (12 papers, 2005 to 2025). A malignant, usually aggressive tumor composed of atypical, neoplastic melanocytes. "Beyond OSCC, WNT2 overexpression has been linked to various malignancies, including colorectal, gastric, pancreatic cancer, melanoma and non-small cell lung cancers." (PMID 40453074, 2025). "In human melanoma models, monoclonal antibodies targeting WNT2 induce apoptosis in WNT2-overexpressing melanoma cells, sparing normal cells." (PMID 40453074, 2025). "In contrast, analyses of a melanoma cDNA array (GEO: GSE108969) showed that the mRNA levels of nearly all Wnts (except Wnt2 and Wnt8b) were significantly greater than those in NHEMs and primary tumors and metastases." (PMID 38388496, 2024). "There are even more Wnt ligands, such as Wnt2 and Wnt7a, that have been described to have tumor suppressive effects on different cancer types and on melanoma cells (Wnt2)." (PMID 38388496, 2024). "The inhibition of Wnt2 signaling by Wnt2 monoclonal antibody also similarly induced cell apoptosis and inhibited the tumor growth of several malignancies including melanoma, pleural mesothelioma, and NSCLC." (PMID 32923386, 2020). "A monoclonal antibody against Wnt2 was shown to induce apoptosis in vitro in lung cancer, mesothelioma, and malignant melanoma." (PMID 24212796, 2011). "RNAi of candidate Wnts identifies Wnt1, Wnt2, Wnt3, and Wnt7b as the specific isoforms mediating autocrine Wnt signaling in tumor cell lines M14 (melanoma), NCI-H23 (NSCLC), PA-1 (teratocarcinoma), and Hs578T (breast), respectively." (PMID 20856934, 2010). "Also, an anti-Wnt2 monoclonal antibody induces apoptosis in malignant melanoma cells and inhibits tumor growth." (PMID 34901211, 2021). "Although high levels of WNT2, WNT7B and WNT10B are reported to activate WNT/β-catenin signalling, several studies report a reduction in nuclear β-catenin staining in high-risk melanoma patients." (PMID 23129487, 2012). "WNT2 has also been found to be overexpressed in malignant melanoma." (PMID 22007305, 2011). "In particular Wnt-2, a survival factor in human carcinogenesis, has lately become focus of intensified research as a biomarker and a potential target to subclassify and treat malignant melanoma." (PMID 22007305, 2011). "Also, Wnt2 antibody treatment in nude mice with melanoma tumors stopped tumor growth." (PMID 24212796, 2011). "In NCI-H23 NSCLC cells and in M14 melanoma cells, potentiation of autocrine Wnt signaling by YW211.31 antibody and antagonism by YW210.09 are consistent with Wnt2 RNAi inhibiting endogenous signaling in NCI-H23 cells, and with endogenous Wnt1 expression in M14 cells." (PMID 20856934, 2010).
colon carcinoma (11 papers, 2007 to 2024). "Cancer associated fibroblast was proved to promote colon cancer angiogenesis via increasing WNT2." (PMID 37237274, 2023). "WNT2 is known to be up-regulated in colon cancer and this up-regulation may be an underlying cause of oncogenesis." (PMID 21575255, 2011). "CAF-derived wingless-type MMTV integration site family member 2 (WNT2) increased tumor angiogenesis in colon cancer, and its overexpression increased blood vessel density and tumor volume in CRC xenografts." (PMID 38193080, 2023). "This was further underscored by the correlation of WNT2 expression with potential angiogenic markers in human colon cancer samples." (PMID 31667643, 2020). "Overexpression and autocrine of WNT2 (Wnt Family Member 2) in CAFs can promote colon cancer proliferation, invasion and metastasis in vitro and in vivo." (PMID 33125346, 2020). "Wnt2 and Wnt5a expression are also elevated in colon cancer compared to normal colon and during the progression from adenoma to carcinoma." (PMID 28147310, 2017). "In colon cancer, WNT2 might bind to FZD3 to upregulate AXIN2, as well as RNF43 for its negative feedback regulation, in which the modification and degradation of β-catenin are key pathway events in tumor progression." (PMID 39228892, 2024). "Taken together, these data strongly support the hypothesis that elevated WNT2 in CAFs of colon carcinoma exerts a pro-angiogenic function as overexpression increased angiogenic properties and knockdown repressed endothelial structure formation." (PMID 31667643, 2020). "WNT2 expression in CAFs led to autocrine activation of canonical Wnt signaling and enhanced fibroblast motility, which in turn positively affected invasive and metastatic potential of colon cancer cells." (PMID 31667643, 2020). "In our experimental approach to study the effects of WNT2 on colon cancer angiogenesis, we only use direct cell–cell contact to assure proper induction of signaling, as WNT signaling in most cases is dependent on the direct contact of WNT-producing and responding cells." (PMID 31667643, 2020). "Thus, our results indicate the possibility that elevated levels of WNT2 in human colon cancer are involved in increased tumor angiogenesis." (PMID 31667643, 2020). "In summary, these data underscore the in vivo relevance of our conclusion drawn from the in vitro experiments, further strengthening our hypothesis that stroma-derived WNT2 is a prominent angiogenesis-promoting factor in colon cancer." (PMID 31667643, 2020). "Other alterations in Wnt pathway components, including LEF1, Fz receptors and Wnt2 and Wnt5a have been described in colon cancer which may contribute to regulation of Wnt signal throughput." (PMID 17386109, 2007). "Thus, we addressed the role of WNT2 on tumor angiogenesis in colon cancer." (PMID 31667643, 2020). "Among them, WNT2 is an important component in the WNT signaling pathway and promotes tumor angiogenesis in colon cancer." (PMID 35992347, 2022). "The colon cancer cell line, RKO, responded to Wnt3a CM, Wnt2 and Wnt1 by increasing canonical Wnt pathway throughput." (PMID 17386109, 2007). "However, if there is a role for WNT2 in colon cancer, angiogenesis was not addressed so far." (PMID 31667643, 2020). "Wnt2, but not Wnt3a, abrogated Fz4 expression in NCM460, but not in RKO or another colon cancer cell line, HCT116." (PMID 17386109, 2007).
lung cancer (10 papers, 2012 to 2022). A malignant neoplasm involving the lung. "A protein frequently upregulated in gastrointestinal cancers, but also in other cancers, such as cervical, pancreatic, and lung cancer, is Wingless-type MMTV integration site family member 2 (WNT2)." (PMID 31667643, 2020). "Among the 50 lung cancer samples, we identified a 91% correlation between the transcriptional increase of Wnt-2 and Frizzled-8 (p<0.05)." (PMID 23815780, 2013). "Semi-quantitative RT-PCR was used to identify the expression of Wnt-2 and Frizzled-8 in 50 lung cancer tissues from patients." (PMID 23815780, 2013). "Wnt-2 plays an oncogenic role in cancer, but which Frizzled receptor(s) mediates the Wnt-2 signaling pathway in lung cancer remains unclear." (PMID 23815780, 2013). "Whether the activation of Frizzled-9 receptor in Wnt-2 signaling is to promote or suppress the development of lung cancer is unknown." (PMID 23815780, 2013). "Inhibition of Wnt-2 signaling with dnhWnt-2 construct may provide a new therapeutic avenue for targeting the Wnt pathway in lung cancer." (PMID 23815780, 2013). "Both Wnt-1 and Wnt-2 are up-regulated in non-small cell lung cancer (NSCLC), whereas Wnt-7a is down-regulated in most lung cancer cell lines and tumor tissues." (PMID 23815780, 2013). "Our results thus far demonstrate that SOX2 regulates the transcriptional network of oncogenes, including WNT1, WNT2, NOTCH1 and c-MYC and promotes the tumorigenesis of human lung cancer cells." (PMID 22615765, 2012). "In this regard, our results demonstrated that silencing of SOX2 significantly reduces the protein expression level of oncogenes-WNT1, WNT2, c-MYC and NOTCH1 in human lung cancer and further revealed other target cancer genes of SOX2." (PMID 22615765, 2012). "For example, differential expression of several WNT components including WNT1, WNT2, WNT7A, DVL3, β-CATENIN and APC, have been reported in normal lung tissues and lung cancers, particularly in NSCLC (non-small cell lung cancer)." (PMID 22846383, 2012). "Although the frizzled family of receptors are known to function as key components of the Wnt signaling pathway, specific interactions of Wnt-2 with its receptor(s) have not been determined in lung cancer." (PMID 23815780, 2013). "In addition, anti-WNT2 antibodies could induce specific apoptosis in NSCLC by inhibiting WNT signaling, making anti-WNT2 monoclonal antibodies one of the strategies for treating lung cancer." (PMID 35957916, 2022). "In addition, higher expression of the oncogenes c-MYC, WNT1, WNT2 and NOTCH1 was detected in side population (SP) cells than in non-side population (NSP) cells of A549 lung cancer cells, indicating a possible mechanism for the tumorigenic potential of CSC’s." (PMID 23349823, 2013).
esophageal cancer (9 papers, 2016 to 2025). A primary or metastatic malignant neoplasm involving the esophagus. "Esophageal cancer specimens exhibit co-overexpression of Wnt2 and Wnt5A, as well as receptors such as FZD2 and FZD6, which are linked to worse prognosis and reduced survival." (PMID 40943055, 2025). "One study found that Wnt ligand proteins (Wnt 1, Wnt2, and Wnt7A) were significantly upregulated in esophageal cancer, glioblastoma, and OC." (PMID 31462944, 2019). "Esophageal cancer micro environment factor WNT2 was critical in cancer metastasis." (PMID 32766155, 2020). "In a previous study, it was demonstrated that WNT2 protein could be secreted by fibroblasts to promote the progression of esophageal cancer." (PMID 33222684, 2020). "Tumor fibroblast cells also secrete WNT2, which acts as a growth and invasion-promoting factor by activating the canonical WNT/β-catenin signaling pathway in esophageal cancer cells." (PMID 27513465, 2016). "Furthermore, we confirmed the promoter region of WNT2 was hypermethylated in three esophageal cancer cell lines (EC9706, EC109, and EC1) while no methylation was detected in normal esophagus epithelial cells (Het-1A)." (PMID 32699215, 2020).
non-small cell lung carcinoma (9 papers, 2009 to 2025). A group of at least three distinct histological types of lung cancer, including non-small cell squamous cell carcinoma, adenocarcinoma, and large cell carcinoma. "Wnt2 promotes gastrointestinal tract cancer and non-small cell lung cancer progression by activating Wnt/β-catenin pathway." (PMID 28665975, 2017). "Wnt-2 overexpression is thought to be involved in human lung carcinogenesis and inhibition of Wnt-2-mediated signaling induces programmed cell death in non-small-cell lung cancer cells." (PMID 23320038, 2012). "Unlike our results, Wnt2 was reported to be increased in human non-small cell lung cancer tissues." (PMID 19812696, 2009).
autism (8 papers, 2010 to 2022). Persistent deficits in social interaction and communication and interaction as well as a markedly restricted repertoire of activity and interest as well as repetitive patterns of behavior. "Specifically, Wnt2, located in the putative speech and language region at chromosome 7q31-33, has been identified as a susceptibility gene for autism." (PMID 24656144, 2014). "Moreover, Wnt2 genes found in the autism susceptibility chromosomal locus and several Wnt2 variants are associated with ASD." (PMID 35296811, 2022). "This study involved a case–control study of 9 single-nucleotide polymorphisms (SNPs) within the WNT2 gene in 170 autism patients and 214 controls from Japan, and a follow-up of the positive results in a transmission disequilibrium test (TDT) in 98 Japanese autistic family trios." (PMID 23083465, 2012). "Given the similarities between autistic disorders and schizophrenia (as a neurodevelopmental disorder), we investigated whether WNT2 gene variations act as risk factors for schizophrenia in a Korean sample." (PMID 20492734, 2010). "Previously, several studies have addressed whether the WNT2 gene is associated with autism, a neurodevelopmental disorder." (PMID 20492734, 2010). "The significant associations from the initial part were replicated in the TDT part and the authors concluded that “WNT2 is a strong candidate gene for autism”." (PMID 23083465, 2012). "Neuronal differentiation- and survival-associated genes, such as wingless-type MMTV integration site family member 2 (WNT2) and homeobox A1 (HOXA1) were also reported as autism susceptibility genes." (PMID 21935445, 2011). "The WNT2 gene and its chromosomal location have received attention as a candidate gene with regard to autism." (PMID 20492734, 2010). "Association studies investigating WNT2, DISC1, MET, DOCK4 or AHI1 also provide evidence that the canonical Wnt pathway might be affected in autism." (PMID 23083465, 2012). "Thus, a too-strong Wnt2 signaling could lead to enhanced midbrain dopamine function, which eventually might relate to the repetitive behaviors seen in autism patients." (PMID 23083465, 2012). "The WNT2 gene (Wingless-type mouse mammary tumor virus integration site family, member 2) [OMIM:147870] is a candidate gene for autism." (PMID 22050706, 2011). "Some have been associated with neurodevelopmental disorders: schizophrenia (DIXDC1, ARVCF, MAGI2, ZIC2), ADHD (attention deficit/hyperactivity disorder) (TCERG1L), movement disorders (NOL3, TP53INP2), Huntington’s disease (H2AFY2, AGPAT1), Parkinson’s disease (LMX1B), and autism (PLXNA4, WNT2)." (PMID 25748564, 2015).